PVT1 (Pvt1 oncogene)
Diseases named in the same sentence as PVT1 in open-access papers (continued):
Sharing a sentence is not in itself a finding about the gene and the disease.
cancer (continued). "In this study, we also assessed the association between PVT1 expression and clinicopathological characteristics in nine types of cancers." (PMID 29348896, 2017). "Receiver operating characteristic (ROC) curve was further used to analyze the diagnostic effect of PVT1 in the 21 type cancers." (PMID 29088881, 2017). "Accumulated evidence suggested that PVT1 overexpression was associated with high-risk grade, metastasis, and poor overall survival of cancer patients, and acted as a powerful predictor of tumor progression in a wide range of cancers." (PMID 29348896, 2017). "Previous studies have shown that PVT1 resides in the well-known cancer risk region 8q24 and is amplified in HNSCC." (PMID 29262850, 2017). "Due to PVT1 expression acting as a diagnostic biomarker of cancer, publication bias of test accuracy was checked by a Deek’s funnel plot, which showed that no significant bias existed in tissue (t = 0.39, P = 0.704) and serum (t = −0.47, P = 0.673)." (PMID 29088881, 2017). "In conclusion, this meta-analysis systematically evaluated the association between PVT1 expression and prognosis as well as clinicopathological characteristics in cancer patients." (PMID 29348896, 2017). "PVT1 have been reported to function in multiple biological processes associated with cancer progression, including proliferation, apoptosis and invasion." (PMID 29348896, 2017). "PVT1 is a potential oncogene that has been implicated in a variety of cancers, participating in DNA rearrangements, interacting with MYC and encoding miRNAs." (PMID 29242407, 2017). "The pooled effect showed that diagnostic accuracy of PVT1 for cancers was relatively high in tissue and serum." (PMID 29088881, 2017). "Sensitivity analysis was conducted for the association between cancer diagnosis/detection and PVT1 expression in tissues as well as in serum." (PMID 29088881, 2017). "Accumulating evidences indicated that plasmacytoma variant translocation 1 (PVT1) plays vital roles in several cancers." (PMID 28265576, 2017). "Functional enrichment analysis was carried out to identify PVT1 regulated cancer hallmark processes based on its directed connect mRNAs in normal and tumor ceRNA networks of KICH." (PMID 27580177, 2016). "We next investigated which genomic alterations are the cause of PVT1 increased levels across many different human cancers." (PMID 27366943, 2016). "More importantly, PVT1 expression has been significantly correlated with clinical features such as risk, recurrence, and survival in various cancers." (PMID 27232880, 2016). "Plasmacytoma variant translocation 1 (PVT1) is a highly conserved lncRNA ~50kb downstream of MYC that has attracted significant attention from the cancer field due to its frequent co-amplification with MYC in several solid tumors." (PMID 27232880, 2016). "Both MYC and PVT1 reside in a well-known cancer-risk locus and enhanced levels of their products have been reported in different human cancers." (PMID 27366943, 2016). "Plasmacytoma variant translocation 1 (PVT1), a novel lncRNA, is often up-regulated in various human cancers." (PMID 27588491, 2016). "The long noncoding RNA PVT1 is encoded by a gene that has been long known since it resides in the well-known cancer risk region 8q24." (PMID 25883951, 2015). "More recently, the lncRNA PVT1 has been shown to be dysregulated in several cancers, and it has been functionally linked to cancer tumorigenesis." (PMID 26545364, 2015). "It was demonstrated that PVT1 expression was correlated with the risk-related variant rs378854, and PVT1 expression is required to maintain Myc protein levels and the oncogenic potential of Myc-driven cancer." (PMID 26690121, 2015). "Oncogenes such as MYC, AKT1, AKT2, cyclins CCNA2, CCNB1, CCNB2, CCNE1, CCNE2 and cyclin-dependent kinases CDK1 and CDK4, which were upregulated under androgen treatment, exhibited a significantly reduced expression following PVT1 knockdown, thereby modulating cancer-associated oncogenic pathways." (PMID 41792045, 2026).
cancer (continued). "We hypothesized that loss of the genomic material, and hence the transcript variant(s) at the 3’ end of PVT1, might be advantageous for cancer cells." (PMID 40027648, 2025). "Notably, MEG3, MIAT, Malat1, SNHG20, SNHG12, Ftx, Pvt1, Mir9-3hg expression in cancer immune cells was associated with an immunosuppressive phenotype, while H19, SNHG6, Trp53cor1, MiR17hg and MiR142hg were linked to a pro-inflammatory phenotype in cancer." (PMID 40527978, 2025). "Our analysis reveals that specific lncRNAs, such as MALAT1, HOTAIR, and PVT1, interact with crucial proteins and pathways that govern mitochondrial function and oxidative stress responses, thereby influencing the susceptibility of cancer cells to cuproptosis." (PMID 39325172, 2024). "It has been suggested that the upregulation of lncRNA PVT1 may result in low overall survival rates in different cancers, indicating its diagnostic and prognostic roles." (PMID 38994720, 2024). "Previous studies have verified that miR-145 could be regulated by lncRNA CCAT2 and lncRNA PVT1, which are associated with the malignant phenotype of several cancers." (PMID 38243936, 2024). "Identification of the underlying tumorigenic mechanisms of PVT1 via binding to 4EBP1 could help elucidate its critical role in cSCC carcinogenesis and have important implications for therapeutically targeting cancer." (PMID 36944636, 2023). "PVT1, at the 8q24 chromosomal band, were associated with cancer susceptibility and tumorigenesis." (PMID 37202742, 2023). "Plasmacytoma variant translocation 1 (PVT1) is located in the cancer risk area 8q24.21." (PMID 37396592, 2023). "Multiple PVT1 genetic variants are described as associated with cancer susceptibility." (PMID 34754096, 2022). "Moreover, the extremely high frequency of PVT1 promoter mutations in numerous cancer types indicates its significance to the regulatory process." (PMID 35788171, 2022). "The PVT1 gene encodes a long noncoding RNA that has an oncogenic role in various types of cancer." (PMID 35216288, 2022). "PVT1 is located on the 8q24.21 region recognized as a cancer susceptibility locus." (PMID 35090471, 2022). "Moreover, the relation of chromatin-associated RNAs with cancer progression has been documented in many instances, such as PVT1, H19, MALAT1, and HOTAIR (for a recent review, see reference 45)." (PMID 36445136, 2022). "However, traditionally studies mainly focused on the effects of PVT1 on regulating the efficacy of cancer chemotherapy, few research explored the underlined individual difference." (PMID 35433465, 2022). "Although, in healthy adults, sexual organs appear to be the main sources of some of the most widely reported cancer-associated lncRNAs such as PVT1 and MALAT1 that are mostly expressed in the ovaries of healthy women, while PTENP1 is largely expressed in the testis of healthy men." (PMID 35729321, 2022). "PVT1 has been implicated in the promotion of tumourigenesis and metastasis in various cancers." (PMID 35788171, 2022). "The implications of this study suggest that alternatively spliced transcripts of PVT1, including transcripts containing PVT1 exon 9, may be associated with increased risk of cancer." (PMID 33801373, 2021). "Some studies have reported an association between PVT1 SNPs and cancer." (PMID 35049170, 2021). "Nevertheless, circulatory PVT1 levels had diagnostic and prognostic value in some cancers." (PMID 34322395, 2021). "Interestingly, PVT1, a gene significantly associated with OS survival, is upregulated in cancers through ALKBH5-mediated N6-adenosine methylation." (PMID 35095893, 2021). "Further studies into the upstream regulation of PVT1-encoded miRNAs, including miR-1205, could reveal insight on how miRNAs could be underexpressed in cancers." (PMID 34386489, 2021). "Similarly, SNPs associated with cancers have been shown to be located within intron 1 of PVT1 which can modify promoter strength of the gene." (PMID 33499210, 2021).
cancer (continued). "PVT1 is an important oncogenic lncRNA which has critical effects on onset and development of various cancers, however, the underlying mechanism of PVT1 functioning in ccRCC remains largely unknown." (PMID 34321604, 2021). "FOXM1 promoted cell viability and reduced FOXM1 could rescue circular influence of circular PVT1-caused carcinoma induction." (PMID 33391456, 2021). "Modulating the functions of PVT1 where implicated in cancer may give rise to successful anti-cancer therapies." (PMID 32117705, 2020). "An association between high PVT1 expression and poor prognosis was reported in several cancers." (PMID 32992461, 2020). "Furthermore, the location of the PVT1 gene is considered to be a cancer risk genomic locus, primarily because it shares such a region with MYC, which is a well-studied oncogene." (PMID 33291485, 2020). "The gene that encodes lncRNA PVT1 resides in the well-known cancer-risk region of chromosome 8q24." (PMID 33126409, 2020). "In order to further investigate the association of PVT1 with a variety of cancer development, we summarized the effects of PVT1 inhibiting on malignant phenotypes (including proliferation, metastasis, invasion, and apoptosis) and its diverse molecular mechanisms 21, 28-70." (PMID 31897242, 2020). "PVT1, a long non-coding RNA has been implicated in a variety of human cancers." (PMID 32117705, 2020). "Emerging evidence of Genome-wide association study had demonstrated that SNPs located in PVT1 might be used as susceptibility factors to several cancers." (PMID 31897242, 2020). "Consequently, PVT1 was identified as a prognostic marker for cancer patient’s overall survival, and elevated PVT1 expression was found to associate with advanced tumor severity stage according to the tumor-node-metastasis (TNM) classification scheme." (PMID 33329688, 2020). "Therefore, most studies have shown that PVT1 fusion genes exert the effect of affecting cancer risk mainly by driving protein expression." (PMID 31309249, 2019). "Moreover, lncRNA PVT1 shares a recognized cancer risk locus with the nearby, well-known MYC oncogene." (PMID 30925926, 2019). "There is substantial interest in whether this tumor suppressor-PVT1 promoter might serve as a therapeutic target in PVT1 promoter-mutated cancers with Myc being the cancer driver." (PMID 31497532, 2019). "There are several advantages of utilizing PVT1 as a diagnostic biomarker of cancer." (PMID 31497532, 2019). "Likewise, plasmacytoma variant translocation gene 1 (PVT1) expressions in cancer tissues were higher than paired healthy controls." (PMID 31632195, 2019). "Herein, we summarize current knowledge regarding the regulatory effects of PVT1 in cancer progression, as well as the related underlying mechanisms, such as interaction with Myc, modulation of miRNAs, and regulation of gene transcription and protein expression." (PMID 31497532, 2019). "Additionally, circular transcript variants of PVT1 have been shown to act as microRNA sponges in various cancers." (PMID 31357500, 2019). "However, some well-established transcription factors involved in cancer cell proliferation share a common thread of microRNA associations with PVT1." (PMID 31249809, 2019). "Furthermore, copy numbers of the lincRNA PVT1 are increased in more than 98% of cancers that have increased copy numbers of MYC, and high expression levels of PVT1 are associated with a poor prognosis in various cancer patients." (PMID 31801944, 2019). "PVT1/Myc co-operation plays a fundamental role in cancer associated with 8q24 gain." (PMID 31497532, 2019). "The human PVT1 gene is located in 8q24, which is widely recognized as a cancer-associated region." (PMID 31380270, 2019). "Together, these results suggest that PVT1 may have a critical role in cancer progression, and might serve as a diagnostic or prognostic indicator for cancer." (PMID 31497532, 2019). "PVT1 is an lncRNA which has been shown to be associated with poor prognosis in many cancers." (PMID 29701689, 2018).
cancer (continued). "Moreover, PVT1 lies in a recognized cancer risk locus that it shares with MYC and shows highly complex gene architecture." (PMID 28187158, 2017). "Based on these studies and owing to its functions, PVT1 may be a consequential biomarker of cancer, and also be one of the causal factors for tumorigenesis in general." (PMID 29348896, 2017). "Moreover, PVT1 expression was significantly correlated with clinical features, such as risk, recurrence, and survival in various cancers." (PMID 28938549, 2017). "In order to clarify the association between PVT1 expression and clinical outcomes in cancer patients, we conducted a meta-analysis of 15 studies including 1711 patients to assess the effect of PVT1 expression on overall survival of patients with various cancers." (PMID 29348896, 2017). "Through the use of chromosome engineering in mice and both loss and gain-of-function analyses in different human cancer cell lines, it was demonstrated that PVT1 was required for high MYC protein expression, via its capacity to protect MYC from phosphorylation and subsequent degradation." (PMID 27077133, 2015). "However, the PVT1 transcript also maps to this region and has been implicated in cancer pathophysiology as well." (PMID 25890171, 2015). "Moreover, PVT1 lies in a recognized cancer risk locus that it shares with the well-known MYC oncogene." (PMID 25883951, 2015). "PVT1 is upregulted in prostate cancer and associated with cancer development." (PMID 26517688, 2015). "Furthermore, ncRNAs such circRNA_0000140 34, exosomal lncRNA PCAT1 35, lncRNA ODRUL 36, and circular RNA PVT1 37 have the ability to influence the metastasis of cancer and may function as biological markers for diagnostic and prognostic purposes." (PMID 40959103, 2025). "In addition, the differences in the function of lncRNA PVT1 in different studies may be caused by the diversity of therapeutic drugs and cancer cell lines." (PMID 38098223, 2024). "The overexpression of plasmacytoma variant translocation 1 (PVT1) lncRNA located on chromosome 8q24, has been reported to play an important role in tumor progression and biological processes, such as apoptosis, invasion, mobility, and proliferation in various types of cancer." (PMID 33980320, 2021). "Furthermore, PVT1 polymorphisms were regulated the prognosis of cancer, too." (PMID 31897242, 2020). "However, these associations may vary among cancer types and the specific PVT1 isoform (linear or circular), clearly suggesting the need to disentangle their biological function at cellular level." (PMID 32228602, 2020). "Thus, the mutation of PVT1 promoter will be the last straw in cancer development." (PMID 31309249, 2019). "Moreover, the role of PVT1 in cancer development is closely linked to microRNAs (miRNAs)." (PMID 31380270, 2019). "Increased PVT1 level may be associated with poor prognosis in many cancers." (PMID 27588491, 2016). "Long non-coding RNAs, such as PVT1, play key roles in cancer, particularly by regulating gene expression." (PMID 41792045, 2026). "Studies have shown that PVT1 can promote cell growth and prevent cell death in ovarian and cancer of the breast cells." (PMID 41459628, 2026). "There is strong evidence that PVT1 promotes the growth and spread of cancer of the breast in both laboratory and animal studies." (PMID 41459628, 2026). "PVT1 is upregulated in several cancer types and has been shown to interact with the androgen receptor in prostate cells." (PMID 41792045, 2026). "Genomic rearrangements in PVT1 are prevalent in human cancers and result in asymmetric enrichment of the 5’-PVT1 region." (PMID 40027648, 2025). "A unique feature of some tumors from group 3 MB is gene fusions involving MYC and Plasmacytoma Variant Translocation 1 (PVT1), a long non-coding RNA implicated in a variety of human cancers." (PMID 40365336, 2025).
cancer (continued). "Our results identify MYC/PVT1 amplification and PVT1 translocation as key drivers of cancer pathogenesis, reshaping the oncogenic signaling landscape through the expression—or lack thereof—of previously uncharacterized short proteins." (PMID 40027648, 2025). "Plasmocytoma Variant Translocation 1 (PVT1), a long non-coding RNA (lncRNA) adjacent to MYC on chromosome 8 is a rearrangement hotspot in many MYC+ cancers." (PMID 40027648, 2025). "We therefore propose that rearrangement at PVT1 is a sophisticated mechanism exploited by cancer cells to sculpt the oncogenic landscape of MYC-driven malignancies." (PMID 40027648, 2025). "Unlike other recurrent gene fusions, such as EWS-FLI1, BCR-ABL, and EML4-ALK, which are preferentially enriched in specific cancer subtypes, PVT1 gene fusions occurred across cancer types." (PMID 40027648, 2025). "PVT1 is located on the 8q24 along with c-Myc which well-reported site for copy number gains in different cancers." (PMID 40265030, 2025). "Full-length PVT1 was observed to be an inhibitor of type I interferon signaling in some cancer models." (PMID 40024473, 2025). "Our study thus identifies a key mechanism by which rearrangements at the PVT1 locus activate additional oncogenic pathways that synergize with MYC to exacerbate the aggressiveness of MYC+ cancers." (PMID 40027648, 2025). "The PVT1 (Plasmacytoma variant translocation 1) lncRNA is located approximately 50 kb downstream of the MYC proto-oncogene and is frequently co-amplified with MYC in various cancer types." (PMID 40743223, 2025). "Specific lncRNAs, such as PVT1, have been found to promote cancer progression by influencing the TME." (PMID 41335135, 2025). "The colon cancer associated transcript 1 (CCAT1) is a lncRNA gene that exists in the sparsely protein coding and highly cancer associated locus of 8q24.21, where both MYC and PVT1 also reside." (PMID 40521240, 2025). "PVT1 is frequently co-amplified with MYC in cancers and promotes MYC protein stability and activity." (PMID 41190324, 2025). "The circRNA hsa_circ_0001821 also known as circPVT1, originates from exon 2 (410 nt) of plasmacytoma variant translocation 1 (PVT1) gene (8q24), a widely recognized region associated with cancer risk." (PMID 38568056, 2024). "We found that PVT1 expression was significantly higher in liver metastasis, compared with primary cancer and regional lymph node metastasis." (PMID 39376555, 2024). "On top of that, PVT1-specific CTLs were present both in the form of TILs and circulating T cells in the cancer patients." (PMID 38731892, 2024). "This negative regulation of MYC expression together with the fact that mutations in the PVT1 promoter frequently occur in human cancers suggest a rather tumor suppressive role for the PVT1 locus and promoter in human cancers." (PMID 37782337, 2024). "Histone acetyltransferase 1 (HAT1) is one of the upstream mediators of PVT1, which determines the cancer cells’ resistance to gemcitabine." (PMID 38559560, 2024). "It has been shown that PVT1 interacts with TME elements to support cancer cell survival and apoptosis resistance." (PMID 39325172, 2024). "A positive correlation between serum PVT1 levels and the expression of PVT1 in cancer tissues has been reported, suggesting PVT1 as a potential diagnostic biomarker for CC." (PMID 38434620, 2024). "PVT1 promotes cell proliferation and cancer stem-cell-like properties of HCC by binding to and stabilizing the RNA-binding protein NOP2." (PMID 39280246, 2024). "Plasmacytoma variant translocation 1 (PVT1) is a non-coding RNA transcribed from a gene located in the 8q24 chromosomal region, which has been implicated in multiple cancers." (PMID 38731853, 2024). "Frequently amplified in cancer, PVT1 offers a striking example of the challenges encountered when studying cancer lncRNAs." (PMID 39195572, 2024). "It has been shown that PVT1 upregulates simultaneously with hypoxia inducible factor 1 subunit alpha (HIF-1α) in hypoxic-cancer cells." (PMID 38559560, 2024).